IL1B (interleukin 1 beta)
Diseases named in the same sentence as IL1B in open-access papers (continued):
Sharing a sentence is not in itself a finding about the gene and the disease.
asthma (continued). "The obese asthma phenotype is also related to the increased production of pro-inflammatory cytokines—TNF-α and IL-1β in the lung, and IL-6 in serum." (PMID 37367676, 2023). "Various experiments on the effects of NPs on lung disorders, such as asthma, COPD, and other lung diseases, indicated that nanoparticles suppressed proinflammatory mediators, such as IL-6, IL-8, IL-1β, and TNF-α." (PMID 37538179, 2023). "NLRP3 activation mainly induces IL-1β secretion through M1 macrophages, thereby inducing AHR, which is considered to be a major characteristic of asthma." (PMID 38292857, 2023). "Beyond Th2 cytokines, SAT also reduced the levels of other potent proinflammatory cytokines (IL-1β, IL-6, and TNF-α) which also plays a key role in asthma pathophysiology and progression, accounting to disease severity." (PMID 36312895, 2022). "IL-17 also enhances IL-1β-mediated IL-8 release from HASM cells, and the IL-17/Th17 axis is involved in microbiomes in the development of asthma." (PMID 35626330, 2022). "In our study, HDM stimulation upregulated FGF2 expression levels in both AECs and the asthma mouse model, and FGF2 pre-treatment recruited subepithelial neutrophils in vivo and promoted IL-1β-induced IL-6 and IL-8 secretion in vitro." (PMID 35093168, 2022). "Allergic events (asthma or cow’s milk allergy) and atopic dermatitis were also positively correlated with EDN, IL-1β, IL-10, and IL-6 at four and six weeks." (PMID 35628877, 2022). "ILC1/2/3 are increased in the sputum of asthma patients; the recruitment of ILC2 is mediated by CCL1, while their differentiation into ILC1 and ILC3 subtypes is facilitated by IL-1β, which is also produced by mast cells." (PMID 35266441, 2022). "Proinflammatory cytokines such as IL-1β, IL-6 and TNF-α are found in increased amounts in the sputum and BALF of patients with asthma." (PMID 35804727, 2022). "Moreover, enhanced production of the proinflammatory cytokine IL-1β following bacterial lipopolysaccharide (LPS) activation of cord blood was observed in individuals at risk of childhood-onset asthma, in association with increased SMAD3 methylation and maternal asthma status." (PMID 35990635, 2022). "IL-1β, IL-6, and MMP-9, which are regulated by the NF-κB pathway, are major mediators of airway inflammation and remodeling in asthma." (PMID 36313381, 2022). "In an OVA-induced model of asthma, treatment with OLT1177 reduced the secretion of IL-1β, Th2 type cytokines (IL-4, IL-5, IL-13) and proinflammatory cytokines (IL-6, TNF-α) in BAL." (PMID 36203607, 2022). "Several studies reported that the expression of TNF-α, TGF-b, IL-1B, and α-SMA genes is significantly increased in OVA-induced asthma in animals, which is consistent with our findings." (PMID 35774748, 2022). "IL6, IL-1β, TNF, VEGFA, AKT1, etc., played an essential role in the PPI network, indicating the crucial roles in treating asthma and IPF." (PMID 35672815, 2022). "The administration of MCC950 to a toluene diisocyanate-induced asthma model blocked the activation of NLRP3 and downregulated protein expression of caspase-1, IL1β, and IL18." (PMID 36189256, 2022). "CSE treatment was able to produce considerable improvement in concentration of IL-1β and LTD-4 in BAL fluid with statistical significance of p < 0.05 and p < 0.01 respectively, after comparing with asthma control group (S) animals." (PMID 38143476, 2022). "When activated by FcεRI, mast cells release IL-1β, IL-6, IL-13, and TNF-α, which are involved in the pathology of asthma." (PMID 35266441, 2022). "CAD significantly decreased the content of TNF-α, IL-13, IL-4, IL-1β and IL-5 in the bronchoalveolar lavage fluid (BALF), IL-17, IL-6, and OVA-specific IgE in serum and increased serum IFN-γ in asthma mice." (PMID 36213326, 2022). "M1 macrophages and M1 cytokines (IL-6, IL-1β, and TNF-α) are involved in neutrophilic airway inflammation in asthma." (PMID 35572500, 2022).
asthma (continued). "The Haemophilus-predominant subgroup had decreased α diversity and enhanced proinflammatory mediators, IL-1β and TNFα, consistent with previous observations in both COPD and asthma." (PMID 33332995, 2021). "Study has found that asthma was more severe in patients with excessive cytokine expression, such as IL6, IL1B, and TNF-α." (PMID 34221070, 2021). "IL-6 and IL-1β production by PBMCs in response to HDM and LPS were impaired in children with asthma in our study." (PMID 34220812, 2021). "In asthma, symptomatic patients’ sputum and BALF contain higher levels of IL-1β than asymptomatic patients, implying inflammasome activation." (PMID 34202842, 2021). "In a murine model of severe, steroid-resistant asthma, the administration of either a neutralizing anti-IL-1β antibody or a pharmacological NLRP3 inhibitor (MCC950) suppressed lung IL-1β production and neutrophilic airway inflammation." (PMID 35055325, 2021). "In this study, for the first time, we found that CCL21 levels in patients with asthma were lower than those in healthy controls, and the levels of IL-1β, IL-6, and TNF-α were higher in patients with asthma than in healthy controls." (PMID 33503170, 2021). "Further, inflammasome activation and subsequent IL1β expression, known to be present in COPD, has been shown to drive experimental severe, steroid-resistant asthma." (PMID 34098956, 2021). "In this study, we examined the serum levels of CCL21, IL-1β, IL-6, and TNF-α in patients with asthma and healthy controls." (PMID 33503170, 2021). "Our finding of a significantly lower level of IL-6 and IL-1B in response to HDM and LPS in the asthmatic group is in concordance with the previous study that reported lower expression of TLR4 in asthma." (PMID 34220812, 2021). "In contrast, both IL-1β and IL-6 production were significantly lower in response to HDM and LPS in children with asthma." (PMID 34220812, 2021). "Ovalbumin administration in mice (a common asthma model) is reported to exhibit its effects via NLRP3 activation and IL-1β secretion." (PMID 34202842, 2021). "Compared to the asthma and COPD groups, higher levels of IL-4, IL-6, TNF-α, IL-1β, IL-17A, and IFN-γ in ACO were observed, and there were significances in IL-4, IL-6, TNF-α, and IFN-γ compared to the control group (P < 0.01)." (PMID 33869177, 2021). "An elevated level of IL-1β indicates pulmonary inflammation, emphysema, and airway remodeling and is increased in the lungs of patients with COPD and asthma." (PMID 32894124, 2020). "Both IL1β and IL1RA are increased in bronchoalveolar lavage fluid during asthma exacerbations in humans." (PMID 32204425, 2020). "MiR-146-5p targets inflammatory mediators like COX2, IL-1β, KIT, NFKB1, TLR4, TRAF6, and UHRF1 and has been proposed as a predictor for asthma exacerbations in childhood asthma." (PMID 32998415, 2020). "IL-1β, a potent inflammatory cytokine, was involved in multiple chronic inflammatory diseases, including chronic obstructive pulmonary disease (COPD) and asthma." (PMID 32423405, 2020). "A previous study has found that CXCL8 and IL-1β expression was promoted in both COPD and asthma patients." (PMID 32756014, 2020). "This indicates that IL-1β and NLRP3 play an important role in neutrophilic asthma inflammation and in COPD." (PMID 32509795, 2020). "A high number of positive correlations between the assessed cytokines and CHI3L1, IL-12p40, IL-1β, IL-6, IL-8, TNF in moDCs was observed in asthma and COPD." (PMID 32842623, 2020). "Higher relative abundance of these bacteria is furthermore associated with an airway immune profile dominated by reduced TNF-α and IL-1β and increased CCL2 and CCL17, which itself is an independent predictor for asthma." (PMID 31676759, 2019). "And the expression of IL-1β and CCL-24 in patients with activation of asthma (N = 9) in 1 year was significantly higher than in children without activation of asthma (p < 0.001 and p = 0.004)." (PMID 31548841, 2019).
asthma (continued). "Therefore, via the production of IL-1β, eosinophils may participate in profibrotic and proinflammatory events leading, for instance, to a Th17/neutrophilic and treatment-refractory phenotype in asthma." (PMID 30906226, 2019). "On univariate analysis, allergic rhinitis in sibling, paternal allergic rhinitis, high expression of eosinophils count, IL-1β and CCL-24, history of active asthma and atopy correlated with severity of AR." (PMID 31548841, 2019). "NLRP3 activation induces IL-1β secretion primarily by M1 macrophage, which induces AHR that is considered as a major feature of asthma." (PMID 30050954, 2018). "We found that YPFS not only significantly inhibited the IL-1β production in vitro, but also decreased its levels in the periphery and lung tissue of OVA-induced asthma mice." (PMID 29311942, 2017). "The blood and sputum of asthma and COPD patients found that IL-1β gene expression was significantly higher than healthy people." (PMID 29254155, 2017). "Obese asthma mice showed a significant increase in airway hyper-responsiveness, airway inflammation, pro-inflammatory cytokine levels and NLRP3 mRNA, IL-1β mRNA expression." (PMID 29160418, 2017). "Changes in Th17 cells correlate with asthma induction, making it important to analyze Th-17 proteins such as TNF-α, IL-6, and IL-1β." (PMID 29151835, 2017). "The LN and LE treatment groups showed reduced levels of IL-1β in their BALF samples (P = 0.039, P = 0.042) compared with the OVA-induced asthma mice." (PMID 27134644, 2016). "Considering the findings in this article, the effects of anti–IL-1β and anti-TNF therapy on interferon responses and asthma exacerbation rates and severity are warranted and would be of interest." (PMID 25630941, 2015). "Cluster 2 contained an asthma and COPD overlap group, with predominately neutrophilic airway inflammation and elevated levels of IL-1β and TNF-α in addition to being assigned the highest proportion of subjects with bacterial colonization." (PMID 25129678, 2015). "And that if the levels of ATP are high, as described in patients with asthma and COPD, the EVs can release IL-1β and IL-18." (PMID 24972036, 2014). "Previous work has suggested that pro-inflammatory cytokines including IL1β and TNFα and cyclic strain also induce MMP-1 expression in ASM and are likely to be of relevance to asthma." (PMID 24587395, 2014). "Elevated levels of IL-1β and TNF-α are reported from BAL fluid of asthma patients and they increase with severity of disease." (PMID 23388501, 2013). "A substantial documentary evidence supports IL-1β and TNF-α as a central players in the pathogenesis and progression of asthma; they are also common in any inflammatory disorder, and can act both locally and systemically." (PMID 23388501, 2013). "Recently, HIF-1α has been demonstrated to be responsible for LPS-induced IL-1β expression in bone marrow derived macrophages; furthermore, HIF-1α activation has been shown to be correlated with chronic diseases such as asthma." (PMID 23935964, 2013). "TSLP can induce multiple signaling pathways in asthma, including STAT6, IL-4, IL-1β and TNFα, p38 and Jun kinase (JNK )." (PMID 24167583, 2013). "Inflammatory cytokines such as TNF-α, IL-1β and IFN-γ play an important role in diseases such as asthma." (PMID 18341691, 2008). "The inflammatory cytokines, IL-1β and TNF-α, and the growth factor, TGF-β1, are thought to play active roles in asthma and emphysema/COPD, and induce the induction of a number of inflammatory mediators by ASMC." (PMID 16359550, 2005). "NLRP3 has a role in pediatric asthma (especially non-allergic or steroid-resistant asthma) with increased serum levels along with IL-1β, and their level in induced sputum positively correlates with the severity of the disease." (PMID 41318536, 2025).
asthma (continued). "Concurrently, Sema3E KO mice that were subjected to the type-2 low asthma model demonstrated an elevated presence of pulmonary neutrophils, dendritic cells, CD4 T cells, as well as increased levels of IL-17, TNF, IL-1β, CXCL-8, and MCP-1/CCL2 in comparison to their WT counterparts." (PMID 40512736, 2025). "Genes such as IL1B and CCL17 exhibited significantly upregulated expression in the patient group, while others, like IFNG and FOXP3, were markedly downregulated (p < 0.05), suggesting their potential roles in asthma pathogenesis." (PMID 40309741, 2025). "Unlike classical type 2 inflammatory cytokines, which did not alter HK2 expression, IL-1β signaling played a pivotal role in HK2 upregulation in asthma." (PMID 40643524, 2025). "Alternatively, proinflammatory cytokines, particularly IL-1β and TNF-α, may amplify the inflammatory response in asthma and COPD and corelate to disease severity." (PMID 40136649, 2025). "Furthermore, this study utilized network pharmacology to identify pivotal asthma treatment targets for YKS, including AKT1, TNF, IL1B, EGFR, IFNG, IL4, CASP3, and PTGS2." (PMID 40420184, 2025). "The IL-1β levels were significantly elevated in the asthmatic group treated with saline (Ast+Sal, 28.06 ± 2.23) compared to both control groups (Ctl+Sal, 18.60 ± 4.62; Ctl+FOR, 17.21 ± 1.64), demonstrating the inflammatory effect of asthma induction." (PMID 40136501, 2025). "IL-1β and TNF-α induce IL-6, which plays a role in inflammation, autoimmunity, cancer, and asthma." (PMID 41155381, 2025). "The marked upregulation of IL1B and CCL17 indicates that the overexpression of these genes may directly influence immune responses in asthma patients." (PMID 40309741, 2025). "Our study showed that the ZLN005 reduced NLRP3 protein expression and IL-18 and IL-1β mRNA levels, suggesting that ZLN005 could alleviate asthma by inhibiting inflammasome activation." (PMID 40343297, 2025). "T2-low asthma is characterized by a predominance of Th1- or Th17-driven immune responses, accompanied by the secretion of cytokines such as IL-2, IL-17, IFN-γ, and IL-1β." (PMID 41155381, 2025). "Inhibiting IL-1β during RSV infection can improve RSV immunopathology and reduce the consequences of allergen-induced asthma, making it a potential new therapeutic target for reducing early virus-induced asthma development." (PMID 40636260, 2025). "This pathway contributes to both the development and exacerbation of asthma by mediating the release of pro-inflammatory cytokines such as IL1β and IL18, which are critical in the pathogenesis of severe steroid-resistant asthma (SSRA) and other asthma phenotypes." (PMID 40598285, 2025). "Mendelian randomization was employed to investigate causal relationships between asthma and core targets like AKT1, TNF, and IL1B, revealing a direct causality with AKT1 but not with TNF or IL1B, suggesting their indirect influence on asthma pathways." (PMID 40420184, 2025). "At the cellular level, human ASM cells treated with TNF-α, IL-1β, and IFN-γ (imitate the inflammatory conditions in patients with asthma) induced an up-regulation of miR-145-5p and a down-regulation of Krüppel-like factor 4 (KLF4), an inhibitor of smooth muscle cell proliferation." (PMID 38337625, 2024). "In “type 2-low” asthma, airway inflammation is mediated by IL-1β, IL-6, and neutrophils, with a lack of Th2 response and low frequencies of blood sIgE antibodies." (PMID 38629073, 2024). "This type of asthma, also termed “non-eosinophilic asthma” or “neutrophilic asthma,” involves IL-6 produced by airway epithelial cells and neutrophils, IL-1β produced following inflammasome activation, and TGF-β produced by neutrophils and eosinophils." (PMID 38629073, 2024). "Considering the strong ability of activated macrophages to secrete inflammatory cytokines like IL-1β, using PI3K inhibitors could potentially reduce asthma symptoms by boosting the protective effects of GLCCI1 in these cells." (PMID 39834584, 2024).
asthma (continued). "In addition, it significantly attenuated the symptoms of asthma attacks, reduced the number of macrophages, lymphocytes, neutrophils, and eosinophils in BALF and inflammatory cytokines, including IL-1β, IL-5, IL-6, and IL-13." (PMID 38579176, 2024). "Likewise, in children with exacerbated and controlled asthma, miR-181a expression negatively correlated with serum levels of TNF-α, IL-1β, and IL-6." (PMID 38337625, 2024). "This study indicates that alongside IL-1β, increased serum iNOS levels could serve as biomarkers for comorbidity of PAR and asthma and decreased lung function." (PMID 38167134, 2024). "Higher expression of NLRP3 and higher levels of IL-1β and IL-18 from severe asthma group in non-stimulated state.Significant increase of IL-1β and IL-18 after NLRP3 activation." (PMID 39554494, 2024). "LPS stimulation significantly increased the pro-IL-1β+CARD11+ population among CD16+ cells in obese individuals with asthma compared to that in obese controls or nonobese individuals with asthma." (PMID 39672814, 2024). "We previously showed that increased IL-1β responses drive steroid-insensitive, inflammation and AHR, and that inhibiting NLRP3 activation with MCC950 reduced IL-1β production and ablated these features in murine models of severe asthma." (PMID 38044426, 2023). "Canakinumab, an IL-1β monoclonal antibody, is no longer being studied as a therapeutic drug for asthma because of its complicated mechanism and unsatisfactory effect." (PMID 37880668, 2023). "Inflammasome-induced IL-1β release from PBMCs from patients with severe asthma was not increased during exacerbation compared to when stable." (PMID 38044426, 2023). "We first assessed the response of PBMCs from healthy subjects and patients with severe and non-severe asthma to NLRP3 inflammasome-induced IL-1β release." (PMID 38044426, 2023). "Increased circulating adipokines, as well as elevated levels of IL-1β and TNF-α are associated with asthma in obese individuals, but not with allergic asthma." (PMID 36803977, 2023). "RV infection at a multiplicity of infection (MOI) 0.1, but not UV-inactivated RV (UV-RV), induced secretion of mature IL-1β 24 h after infection, which was significantly increased in patients with asthma." (PMID 37087523, 2023). "A. alternata also enhanced RV-induced mature IL-1β release in control subjects, whereas in asthma, it potently induced release of mature IL-1β even without RV infection, suggesting a different mechanism of action." (PMID 37087523, 2023). "The current study extends upon these findings by demonstrating, for the first time, that systemic immune cells in clinical asthma have an increased ability for inflammasome-mediated IL-1β release, regardless of asthma subtype." (PMID 38044426, 2023). "In a murine house dust mite model of severe corticosteroid-resistant asthma, i.p. administration of MCC950 completely prevented the development of airway hyperresponsiveness and reduced bronchoalveolar lavage neutrophilia and IL-1β concentrations." (PMID 37598239, 2023). "Regarding the evaluation of inflammatory markers in the airways, we observed that the ACO group, compared to the asthma model (OVA), was higher in cells for IL-1β, IL-10, IL-17, and IFN-γ, with the exception of IL-5 positive cells that were superior in the OVA group." (PMID 37511021, 2023). "In this study, we characterized the ability for inflammasome priming, activation, and IL-1β release from immune cells from patients with severe and non-severe asthma, and healthy controls, and examined the effects of therapeutic suppression with MCC950." (PMID 38044426, 2023). "Again, complementary to IL-1β secretion, ASC specks count was higher in patients with asthma." (PMID 37087523, 2023). "MCC950, potently suppressed IL-1β release from PBMCs from patients with severe (stable and exacerbating) and non-severe asthma and healthy subjects that are stimulated with nigericin alone, LPS alone, or LPS + nigericin." (PMID 38044426, 2023).